OAS2 (2'-5'-oligoadenylate synthetase 2)
Diseases named in the same sentence as OAS2 in open-access papers (continued):
Sharing a sentence is not in itself a finding about the gene and the disease.
OAS2 also shares sentences with these, for which no sentence is quoted: H1N1 virus infection (2 papers); non-small cell lung carcinoma (2); pneumonia (2); squamous cell carcinoma (2); acute monocytic leukemia (1); Alzheimer disease (1); antiphospholipid syndrome (1); arboviral disease (1); astroglioma (1); bovine respiratory disease complex (1); celiac disease (1); diabetic (1); diarrhoea (1); glioblastoma multiforme (1); glomerulonephritis (1); Graves disease (1); infectious disease (1); medulloblastoma (1); neuropathy (1); Pancreas (1); parasite infection (1); periodontitis (1); psoriasis vulgaris (1); Q fever (1); respiratory infection (1); respiratory syncytial virus infections (1); SARS-CoV infections (1); scleroderma (1); Sepsis (1); septic shock (1).
A further 3 diseases each share a sentence with OAS2 in 1 paper.